CDK4 (cyclin dependent kinase 4)
Diseases named in the same sentence as CDK4 in open-access papers (continued):
Sharing a sentence is not in itself a finding about the gene and the disease.
tumor (continued). "Additionally, the tumor was negative for most immunohistochemical markers (CKAE1/AE3, p63, CD23, CD21, MUC4, NUT, CDK4, Pan-TRK, STAT6, SS18, MDM2, Desmin, S100, ERG, TLE1, Fli) and showed only weak and most probably unspecific expression of CD99, CD56, and CD34." (PMID 39519042, 2024). "For instance, recent pre-clinical studies in pancreatic adenocarcinoma suggest that CDK4/6 inhibitors should be administered after (not before) cytotoxic chemotherapeutics since activation of RB1 represses the DNA repair machinery and enhances DNA damage-induced tumor cell death." (PMID 32344731, 2020).
cancer (1,638 papers, 1995 to 2026). A tumor composed of atypical neoplastic, often pleomorphic cells that invade other tissues. "Chemotherapy addresses aggressive disease features, while CDK4/6i, such as abemaciclib or ribociclib, in combination with ET, suppresses residual cancer proliferation to reduce relapse risk." (PMID 40377782, 2025). "Among these therapeutic targets, cyclin-dependent kinases 4 and 6 (CDK4/6) have emerged as critical regulators of cell cycle progression, with their aberrant activation being strongly implicated in tumorigenesis and cancer progression." (PMID 40421216, 2025). "Hyperactivity of the CDK4/6-cyclin D complex results in the loss of control in cell cycle regulation, leading to cell proliferation and cancer development." (PMID 41375037, 2025). "Rb loss has been shown to have synthetic lethality with aurora kinase deficiency, and cancer cells developing RB loss after CDK4/6 inhibition were recently found to be sensitive to a selective aurora kinase A inhibitor." (PMID 40075623, 2025). "Homozygous deletions of CDKN2A, the gene that codes for P16, result in unregulated cell division through disinhibition of CDK4/6 and have been implicated in multiple cancer types, including in BRAF V600E gliomas." (PMID 40094009, 2025). "For example, piR-651, piR-52200, and piR-34971 have been shown to be upregulated in NSCLC, with piR-651 linked to cancer progression, potentially through regulation of cell cycle control proteins such as cyclin D1 and CDK4." (PMID 40949873, 2025). "In contrast, Cdk4-R24C gain-of-function (GOF) mice display increased proliferation, body size, and cancer risk, supporting the notion that CDK4 is a bona fide regulator of cell number in mammals." (PMID 40210435, 2025). "In cancer, deregulation of the individual CDKs is linked to different tumor types with high levels of CDK4 being common in sarcoma, glioma and melanoma whereas overexpression of CDK6 is more frequent in hematologic malignancies." (PMID 39966356, 2025). "In particular, overexpression of cyclin D1 and CDK4/6 is common in cellular transformation toward cancer and has been linked to the dysregulation of oncogenes." (PMID 40723282, 2025). "Considering that VTE ranks as the second major cause of death in cancer patients following cancer progression, there is an urgent need for validated risk scores and effective thromboprophylaxis strategies specifically tailored to CDK4/6i-associated VTE." (PMID 40520154, 2025). "Our results indicate that simvastatin induces G1 cell cycle arrest in TNBCs through the downregulation of CDK4, suggesting that Simvastatin’s anti-cancer effects are associated with its ability to suppress the cell cycle." (PMID 40864776, 2025). "The abnormal expression of cell cycle regulatory proteins, particularly Cyclin D1 and CDK4/6, has often been linked to the onset of different types of cancers." (PMID 40510359, 2025). "Dysregulation of the cyclin D–CDK4/6 complex is linked to various cancers, where increased cyclin D production drives the activation of CDK4/6 and abnormal cell cycle advancement." (PMID 40845025, 2025). "In cancer, hyperactivation of CDK4/6 due to mutation, gene amplification, or mitogen-independent signaling often bypasses Rb-mediated cell-cycle checkpoints, enabling uncontrolled proliferation." (PMID 40894871, 2025). "Cyclin-dependent kinases CDK4 and CDK6 (CDK4/6) are effective targets in cancer therapy since their overexpression and dysregulation are implicated in a wide range of human cancers." (PMID 40696167, 2025).
cancer (continued). "In cancer treatments, CDK2 inhibitors can specifically target CDK2 in cancers where it is a primary driver, minimizing the toxicity and dose limitations associated with inhibiting CDK4 and CDK6." (PMID 40149983, 2025). "Taken together, these data suggest that treatment with CDK4/6i causes consistent and reproducible lysosomal alterations in human cancer cells and biopsies." (PMID 39930269, 2025). "This review provides a comprehensive overview of the current advances in CDK4/6 inhibition in cancer therapy, with a focus on the associated signalling networks and combinatorial treatment strategies." (PMID 40563591, 2025). "Dysregulation of CDK4 has been associated with various diseases, including cancer and neurodegenerative disorders." (PMID 39129166, 2025). "we aim to profile the incidence, clinical characteristics and risk factors of CVAEs associated CDK4/6i to provide a vigilant reference for cancer management." (PMID 40520154, 2025). "While all HR+ patients receive adjuvant endocrine therapy, the addition of the PARP inhibitor olaparib or the CDK4/6 inhibitors abemaciclib or ribociclib is recommended only for intermediate- to high-risk carcinomas." (PMID 39796772, 2025). "So far, research has focused on mutations in the binding interface to CDK4/6, where cancer-related mutations have been shown to critically impair the cell-division inhibiting interaction." (PMID 38951545, 2024). "Development of clinically successful CDK4/6 inhibitors (CDK4/6i) like Palbociclib (PD 0332991), which can cause G1-phase arrest by targeting the Cyclin D-CDK4/6 complexes, has been a significant breakthrough in cancer treatment." (PMID 39796036, 2024). "When screening multiple cancer-related variants, including mutations remote to the CDK4/6-binding interface, we observe that each mutant shows greatly increased amyloid formation propensity." (PMID 38951545, 2024). "Cyclin D1/CDK4-Rb pathway has a significant role in the G1 phase, which is implicated in the development of cancer." (PMID 39161904, 2024). "Dysregulated cell cycle progression, driven by Cyclin-Dependent Kinases 4 and 6 (CDK4/6) and their catalytic subunits D type cyclins, is a hallmark of cancers." (PMID 39695080, 2024). "In CRC and TNBC, miR-545-3p targets CDK4 to inhibit E2F transcriptional activity and causes G1 arrest in cancer cells." (PMID 39027151, 2024). "In the cellular context, C3I-22 treatment reduced the levels of pRb and CDK4 and caused the failure of rapid cell cycle progression in cancer cells as shown by flow cytometry." (PMID 38963708, 2024). "The excitement about dual CDK4/6-SHP2 inhibition has even led to clinical testing of ribociclib (CDK4/6 inhibitor) plus TNO155 (SHP2 inhibitor) in patients with NF1-deficient cancers (NCT04000529)." (PMID 39347707, 2024). "Several molecular mechanisms, including retinoblastoma protein RB1 deficiency, explain CDK4/6 inhibitors resistance in cancer." (PMID 38424044, 2024). "Although CDK4/6 inhibitors show benefit in a subset of cancers, resistance to therapy can arise through spontaneous mutations in RB175 or the overexpression of CDK676." (PMID 39277623, 2024). "Although combining CDK4/6 inhibitors with other targeted therapies can enhance the efficacy of cancer treatment, it also tends to increase the risk of adverse effects." (PMID 39000513, 2024). "Addition of A80.2HCl re-sensitized the resistant cancer cells to CDK4/6i treatment implicated by the enhanced cell cycle gene suppression and colony formation inhibition." (PMID 38424044, 2024). "For example, in the CDK4 gene, a known oncogene that is mutated in a wide range of cancer types, we observed a high density of cSNVs in the coding exons one and six, which are the only coding exons harboring G4s in the CDK4 gene." (PMID 38407356, 2024). "In cancer, mutations or overexpression of CDK4/6 and cyclin D can instigate excessive cell proliferation." (PMID 39254653, 2024).
cancer (continued). "HZ1 exhibits greater potency than CDK4/6 inhibitor in pan-cancer treatment by causing cell cycle arrest and overcomes acquired resistance to CDK4/6 inhibitor." (PMID 38963708, 2024). "Because RB1 is a major downstream effector of CDK4/6 signaling, RB1 loss in cancer cells contributes intrinsic resistance to CDK4/6i1,10–14." (PMID 38424044, 2024). "Targeting of this pathway by CDK4/6i has been shown to exert off-target immunological effects described in mouse models and is associated with response in cancer patients." (PMID 37715207, 2023). "C57BL/6 N mice were immunized with Cdk4 deficient cancer cells or freeze-thawed WT cells on the left flank, and two weeks later re-challenged with live WT cancer cells on the right flank." (PMID 37833461, 2023). "Further discovery proves that CDK4/6 inhibitors upregulate ICAM1 transcription by inhibiting phosphorylation of retinoblastoma protein RB in LKB1 deficient cancer cells." (PMID 36871040, 2023). "Mutations in this gene as well as in D-type cyclins related to Cdk4 was shown to be associated with tumorigenesis of a variety of cancers." (PMID 37836781, 2023). "In the context of cancer, alterations in CDK4/6 activity through gene mutations, deletions, and amplifications are frequently observed." (PMID 38030655, 2023). "Our analysis by GSEA revealed that “DNA sensing pathway” gene sets as “hallmark” signatures were upregulated in Cdk4−/− as compared with vector control MCA205 cancer cells." (PMID 37833461, 2023). "For example, CDK4/6 inhibitors cause myelosuppression in anti-cancer doses but prevent chemotherapy-induced myelosuppression in protective doses." (PMID 36913303, 2023). "An overexpression of KRAS has been associated over the years with many types of cancer growth and development, including breast cancer resistance to CDK4/6i." (PMID 36900131, 2023). "Based on pathological cyclin D1-associated kinase activity, such as in cancer, CDK4/CDK6 expression can be deranged, overexpressed, or altered." (PMID 37190133, 2023). "Of all these CDK-associated interventional cancer studies, CDK4/6 inhibitors account for the major proportion." (PMID 37626854, 2023). "Together, these data demonstrated that Cdk4 and Cdk6 deficiency in cancer cells triggered type I IFNs responses." (PMID 37833461, 2023). "As well as somatic mutations which drive oncogenesis, the cancer cell expresses a range of disparate characteristics including the avoidance of apoptosis, reliance on aerobic glycolysis and Cdk4 overexpression." (PMID 37279947, 2023). "Cell cycle dysregulation caused by aberrant cyclin D1 and CDK4 expression is a major determinant of cancer cell proliferation in MCL." (PMID 37225761, 2023). "Common dysregulations of the CDK4/6-retinoblastoma protein (Rb) axis, like copy-number variation or overexpression as well as loss of negative regulators of the pathway, can lead to cancer formation." (PMID 36817127, 2023). "Recently, CDK4/6 inhibition is reported to cause a profound G1 cell cycle arrest in Rb+ cells, but this phenomenon is transiently in some cancer models." (PMID 36127291, 2023). "By reviewing the current body of literature, it can be seen that approximately 27 miRs or miR clusters have been directly associated with CDK-4/6 therapy in BC or cancer in general." (PMID 37893081, 2023). "Cyclin D is frequently deregulated in human cancer and promotes cell division by activating cyclin-dependent kinase 4/6 (CDK 4/6), causing enhanced cell proliferation and BC progression." (PMID 37762557, 2023). "Our study aims to investigate the protective effect of a probiotic agent, S. boulardii, which can be effective in diarrhea associated with malignancy treatment, CDK4 and CDK6 inhibitors are used in this study." (PMID 36945921, 2023). "Loss of SMARCA4 causes downregulation of cyclin D1, and there are data supporting that this vulnerability mediates drug sensitivity to CDK4/6 inhibition in SMARCA4-deficient cancer cells." (PMID 37446319, 2023).
cancer (continued). "In cancer studies, miR-520a has been associated with suppression of oncogenic signaling pathways including CDK4, SUV39H1, LIMK1, GOT-2, AKT1/mTOR, and PI3K/AKT31–37." (PMID 35149732, 2022). "A high frequency of responsive AS, mainly SE events, were induced by CDK6, CDK4, and PI3K 110α/β level changes, and these AS events finally led to the alteration of the ABCB1 expression and ABCB1-mediated MDR in cdk6 or cdk4 deficient KB-C2 cancer cells." (PMID 35459184, 2022). "The ERBB3 model also plays a role in improving the predictions for CDK4, which is known to participate in inactivating RB gene in many cancers through loss of proliferation control." (PMID 35933367, 2022). "While Rb itself is inactivated in some cancer types, several of its upstream regulators, including p16INK4a, cyclin D1, and CDK4, are more commonly mutated resulting in compromised Rb function." (PMID 35814428, 2022). "Abnormal expression of cyclins D1 and D2 in cancer cells has been discussed as being associated with resistance against CDK4/CDK6 inhibitors." (PMID 35804842, 2022). "PAI-1 has a growth stimulatory effect in cancer cells, causing cyclin D3/cdk4/6 upregulation and cell cycle progression from G1 to S, initiating the progression of cancer cell developments." (PMID 35682652, 2022). "P16INK4A levels have been proposed to cause CDK4/6 inhibitor resistance in different cancer types, but only limited information is available for AML." (PMID 35326705, 2022). "In conclusion, we developed a novel peptide biosensor‐based nano‐probe and succeeded in using it to monitor the cancer‐associated CDK4 kinase activity and the therapeutic response to the CDK4/6 inhibitor in living cells and in vivo." (PMID 35711853, 2022). "While senescence‐linked inflammatory phenotypes caused by classical cancer drugs can be pro‐tumorigenic, senescence induced by CDK4/6 inhibitors lacks NF‐kB‐associated secretory phenotypes and is well tolerated in vivo." (PMID 34985783, 2022). "TSPAN31, recently discovered to be linked to cancer, as natural antisense transcript of cyclin dependent kinase 4 (CDK4), regulates the expression of CDK4 mRNA and protein." (PMID 35120576, 2022). "As a highly selective CDK4/6 inhibitor, palbociclib was expected to have cytostatic effects by causing cell cycle arrest at the G1/S checkpoint, which leads to disruption of cancer cell proliferation." (PMID 35164144, 2022). "The authors suggest that CDK4/6i impairs the ability of cancer cells to recover from chromosomal and DNA damage caused by prior treatment with paclitaxel." (PMID 36185294, 2022). "Of these, clinical data support acquisition of RB1 mutations in a minority of cancers progressing on CDK4/6i, with preexisting loss of functional RB1 associated with poor prognosis on CDK4/6i therapy." (PMID 32940689, 2021). "Aberrant activity of CDK4/6 leads to hyperphosphorylated RB, E2F-mediated progression through G1 and uncontrolled cell proliferation – a hallmark of cancer." (PMID 34025662, 2021). "The mutations of CDK-1 and CDK-4 were carried out using the COSMIC database for CRC coupled with the cBioPortal database for hotspot mutation in human cancers." (PMID 33732631, 2021). "Gain of function mutation in CDK4 is commonly observed in both germline and somatic level of cancers, with the most frequent pattern of CDK4R24C." (PMID 34249677, 2021). "GO enrichment revealed major biological processes and pathways associated with CCND1/CDK4/PLK1/CD44 in different cancers." (PMID 34063946, 2021). "In support of this notion, exploration of data from genomics of drug sensitivity in cancer database showed that loss-of-function mutation of RB1 had highest rank in driving CDK4/6i (palbociclib) resistance across hundreds of cancer cell lines." (PMID 34508104, 2021).